IGF2 (insulin like growth factor 2)
Diseases named in the same sentence as IGF2 in open-access papers (continued):
Sharing a sentence is not in itself a finding about the gene and the disease.
hepatocellular carcinoma (continued). "Insulin-like growth factor (IGF)-2 is overexpressed in hepatocellular carcinoma and accompanying dysplastic lesions." (PMID 12618883, 2003). "In addition, studies have found that miR-615-5p, which downregulates IGF-2 mRNA, is highly expressed in liver cirrhosis and hepatocellular carcinoma tissues, and miR-615-5p targets IGF-2 to inhibit the proliferation of hepatocytes." (PMID 36358907, 2022). "In addition, hepatocellular carcinoma-associated fibroblasts promote α-SMA synthesis and enhance their contractility through IGF-1R and autocrine IGF-2." (PMID 36358907, 2022). "It was suggested that miR-1275 acts as a tumour suppressor in several types of cancers, and miR-1275 overexpression has been reported to inhibit malignant cell behaviours and proliferation in hepatocellular carcinoma simultaneously by regulating oncogenic insulin-like growth factor-2." (PMID 31357957, 2019). "On the other hand, elevated levels of tissue expression of IGF2, IGF1R or other IGF system components (IGFBP7), may indicate an increased risk of hepatocellular carcinoma." (PMID 29702590, 2018). "Type 1 receptor (IGF1R) is reported to interact with insulin-like growth factor 1 and 2 (IGF1 and IGF2) for increasing fibrosis and impair liver functions from the start of preneoplastic alterations up to the developed hepatocellular carcinoma (HCC) stage." (PMID 34336665, 2021). "Increasing evidence shows that IGF1R and its ligands (IGF‐1, IGF‐2) play an important role in the development and progression of several cancers, including hepatocellular carcinoma (HCC)." (PMID 31267557, 2019). "For instance, a combination of flow cytometry and high-density scRNA-seq identified molecular changes in CTCs from hepatocellular carcinoma (HCC) patients and oncogenic drivers such as IGF2." (PMID 35273384, 2022). "In hepatoma models, induced by 2-fluorenylacetamide (2-FAA) in rats, progressively increasing hepatic IGF2 levels during HCC development were observed." (PMID 29702590, 2018). "However, it does not seem to be the case in our system because targeted knockdown of IGF‐2 in the hepatocellular carcinoma cell line Huh7 abolished the migration of MSC‐13, demonstrating that MSC migration toward HCC is dependent on IGF‐2." (PMID 29321953, 2018). "Similar observations were made in thyroid cancer and hepatocellular carcinoma (HCC), where undifferentiated cancer cells preferentially expressed higher levels of INSR-A and produced higher levels of IGF-2 in order to activate the autocrine loop." (PMID 26217584, 2015). "A recent study reportedly showed that AFB1 upregulated both IGF2 and IGF-IR expression in hepatoma cells thereby activating IGF-IR signaling pathway." (PMID 23112878, 2012). "With its secreted ligands, IGF1 and IGF2, Insulin-like growth factor 1 receptor (IGF1R) is highly expressed in many human cancer cells, including gastric (GC) and hepatocellular carcinoma (HCC)." (PMID 22438913, 2012). "With this evidence, IGF2 could be proposed to distinguish between HCA and hepatocellular carcinomas (HCC) in GSD patients." (PMID 33922238, 2021). "Increased expression levels of IGF2, IGF1 and IGFR1 were revealed in animal models of hepatocellular carcinoma (HCC)." (PMID 37298551, 2023). "Indeed, while hepatocellular carcinoma in miR-483 has been demonstrated to be co-expressed with its host gene IGF2, in pterygium, there is a lack of knowledge about this interaction." (PMID 36901760, 2023). "Besides, MBD1 (Methyl-CpG–Binding Domain Protein 1), the partner protein of H19, can induce methylation at H3K9me3 (lysine 9 of histone H3) to differentially methylated regions (DMRs) of correlated imprinted genes like IGF2, SLC38A4 (tumor suppressor in hepatocellular carcinoma) and PEG1." (PMID 36246634, 2022). "Several components of the IGF signaling axis, such as IGF-1, IGF-2 and IGF-1R, are deregulated during HCV-related human hepatocellular carcinoma (HCC)." (PMID 25333772, 2014).
prostate carcinoma (73 papers, 2002 to 2026). A carcinoma that arises from epithelial cells of the prostate gland. "We found that among men with higher serum IGF-2 concentrations, the association of 25(OH)D with prostate cancer was modified by treatment arm (OR, finasteride: 0.84, 95% CI: 0.62–1.14; OR, placebo: 1.33, 95% CI: 1.00–1.65); p for interaction = 0.04)." (PMID 28417914, 2017). "In conclusion, our findings indicate that increased serum 25(OH)D was associated with increased prostate cancer risk among men with higher circulating levels of IGF-2 in the placebo arm of the PCPT study." (PMID 28417914, 2017). "In the placebo arm, above median serum 25(OH)D levels were associated with increased risk of prostate cancer among men with higher IGF-2 (OR:1.33, 95% CI: 1.00–1.65), with a significant interaction between 25(OH)D and treatment arm (Pinteraction = 0.04)." (PMID 28417914, 2017). "While loss of imprinting (LOI) has been reported for two genes in prostate cancer (IGF2 and TFPI2), disease-related changes in methylation across all imprinted gene regions has not been investigated." (PMID 23890537, 2013). "In contrast to normal tissues, where IGF2 is imprinted and only expressed from the paternal allele, loss of imprinting (LOI) and biallelic IGF2 expression are observed in many cancers including prostate cancer (PCa)." (PMID 23781309, 2012). "We did not observe poorer measures of physical capability among carriers of the risk allele for prostate cancer for rs7127900 near IGF2." (PMID 22253814, 2012). "Our results indicate that the association of serum 25(OH)D with prostate cancer in the PCPT may be modified by both serum levels of IGF-2 and treatment arm." (PMID 28417914, 2017). "Higher serum 25(OH)D may increase risk of prostate cancer in the presence of higher circulating IGF-2." (PMID 28417914, 2017). "In the absence of finasteride treatment and under conditions of higher IGF-2, higher levels of serum 25(OH)D may increase prostate cancer risk." (PMID 28417914, 2017). "Indeed, it has been surprisingly demonstrated that high levels of 25(OH)D, in presence of insulin like growth factor 2 (IGF2), may increase prostate cancer risk (OR:1.33; 95% CI: 1.00 to 1.65; p = 0.04)." (PMID 32560347, 2020). "There is some evidence to suggest that SNPs in IGF2 are associated with longevity, measures of adult body size, grip strength, arm and leg strength, and post-exercise muscle damage, and in a GWAS the A allele of rs7127900 near the gene has been associated with increased risk of prostate cancer." (PMID 22253814, 2012). "GATA2 is a critical pioneer TF for AR, trans-activated IGF2 to mediate taxane resistance in prostate cancer or promote chemoresistance in gastric cancer via the EGFR signalling pathway." (PMID 38126976, 2023). "Pyrosequencing analysis of DMRs in corresponding prostate and prostate cancer tissue samples revealed frequent hypo- and hypermethylation at the H19/IGF2:IG DMR in both benign and cancerous tissues." (PMID 35804856, 2022). "KLF4 positively regulates the expression of miR-1, BCL2-interacting killer (BIK) and insulin-like growth factor 2 (IGF2) in prostate cancer." (PMID 33266506, 2020). "On the contrary, genes whose loss/down-regulation was implicated in prostate cancer cell invasion, metastasis formation and worse prognosis (AR, IGF1, IGF2, TGFB3, SEMA3E) were down-regulated in NE-like versus AdenoPCa tumors." (PMID 32041153, 2020). "In prostate carcinoma samples, we found that IGF2 expression can be best explained by differential IGF2 promoter usage." (PMID 29239100, 2018). "Prostate cancer cell exposure to IGF-2 results in a reduced IR-B expression and the relative prevalence of IR-A and IR-A:IR-B ratio is significantly increased in primary human prostate cancers compared to benign tissues." (PMID 30453495, 2018). "In this study, we focused on the identification of major factors that govern IGF2 expression in clinical prostate carcinoma samples." (PMID 29239100, 2018).
prostate carcinoma (continued). "(2011) observed LOI of IGF2 not only in prostatic cancers, but also in adjacent, morphologically normal prostate, suggesting an epigenetic field defect." (PMID 29239100, 2018). "IGF-2 mRNA was increased in samples of patients with castrate resistant prostate cancer and promoted steroidogenesis resulting in activation of the androgen receptor in vitro." (PMID 28417914, 2017). "In conclusion, our analyses reveal a potent role of KLF4 transcription regulation on IGF2 in prostate cancer." (PMID 29017567, 2017). "The IGF2 CNV (gain, loss or normal) was then analyzed in primary prostate cancer tissue samples (7 TUR-BPHs, 38 RP-BPHs and 66 RP-PCas)." (PMID 29017567, 2017). "According to previous reports, IGF2 expression increased during prostate cancer progression in clinical databases." (PMID 28521298, 2017). "IGF2 can activate the IGF1 receptor or insulin receptor or hybrids of these two receptors to contribute to prostate cancer progression to castration resistance." (PMID 25332874, 2014). "Previous studies of loss of imprinting in prostate cancer have focused on TFPI2 and IGF2, with one study reporting lower methylation in the former and three studies providing inconsistent reports of methylation changes in the latter." (PMID 23890537, 2013). "We examined the associations between prostate cancer with polymorphisms of the insulin gene (INS) and its neighbouring genes, tyrosine-hydroxylase and IGF-II (TH and IGF2)." (PMID 12610512, 2003). "While this is not established in ACC tumors, de novo steroidogenesis has been shown to increase after treatment of androgen receptor–positive prostate cancer cells with IGF-2 via upregulated expression of steroid acute regulatory protein (StAR) as well as other steroidogenic enzymes." (PMID 40270996, 2025). "Therefore, we analyzed on cDNAs of 38 selected prostate cancer tissue samples with proven heterozygosity (6 TUR-BPH, 13 RP-BPH and 19 RP-PCa) the imprinting status of IGF2, i.e. one or two allele expression." (PMID 29017567, 2017). "The direction of the association between 25(OH)D and prostate cancer appeared to differ for strata of lower vs. higher IGF-2, but findings were not significant." (PMID 28417914, 2017). "Furthermore, IGF2 increases steroid synthesis, contributing to prostate cancer progression." (PMID 37393293, 2023). "In addition, the loss of IGF2 imprinting was associated with esophageal adenocarcinoma, while the hypomethylation of one of the IGF2 promoters caused dysfunction in the transcriptional regulator Kruppel-like factor 4 (KLF4) in humane prostate cancer." (PMID 32075092, 2020). "Although this was an exploratory analysis, the findings suggest that vitamin D may be associated with increased prostate cancer risk among men with higher IGF-2, and possibly other IGF analytes, in the absence of finasteride treatment." (PMID 28417914, 2017). "We did not observe an increased risk of prostate cancer with higher serum IGF-2 in the PCPT when analyzed previously, in either finasteride or placebo treatment arms, although men in the highest quartile of serum IGFBP-2 had increased risk of total and low-grade prostate cancers." (PMID 28417914, 2017). "However, in prostate cancer, abolished IGF2 expression has also been observed." (PMID 25423083, 2014). "In addition, KCTD11 overexpressing prostate cancer cells displayed a reduction of cell proliferation-related genes, which are known direct targets of Hedgehog/Gli1, such as Cyclin D2 and IGF-2." (PMID 25045667, 2014). "Prostate cancer cell lines PC3, LNCaP and DU145 were analyzed together with three blood DNA samples from healthy donors (controls 1–3) regarding the IGF2 copy numbers using the qBiomarker CNV PCR Assay for Human chromosome 11 tile 10,752 (Qiagen)." (PMID 29017567, 2017).
prostate carcinoma (continued). "Utilizing prostate cancer cell lines LNCaP and DU145, we demonstrated that KLF4 binds to hypomethylated IGF2-DMR0 and affects IGF2 expression in dependence to prevailing post-translational histone modifications." (PMID 29017567, 2017). "In particular, in prostate cancer, it was observed that hypomethylation of IGF2-DMR0 correlates with decreased IGF2 expression." (PMID 29017567, 2017). "The majority of heterozygous prostate cancer tissue samples, suitable for LOI studies (29 out of 38), exhibited maintenance of IGF2 imprinting." (PMID 29017567, 2017). "While studies have suggested a role for IGF2 and tissue factor pathway inhibitor-2 (TFPI2) LOI in prostate cancer, the literature is restricted largely to these two genes." (PMID 23890537, 2013). "Moreover, in prostate cancer, GATA2 has been well-characterized as a critical pioneer TF for AR, whereas GATA2 can mediate PTX resistance by AR-independent regulation of IGF2." (PMID 38126976, 2023). "GATA2 also regulates important non-androgen responsive genes (e.g. IGF2) involved in prostate cancer progression." (PMID 31501863, 2019). "On the other hand, this study found no or little evidence for the association of IGF-2, IGFBP-1, -2, and -3 with increased prostate cancer risk." (PMID 29487568, 2018). "In contrast, the methylation of IGF2/H19-ICR (imprinting control region with a CTCF binding site located between IGF2 and H19 genes) was not significantly different between the prostate cancer groups TUR-BPH, RP-BPH and RP-PCa." (PMID 29017567, 2017). "Overexpression of PLAGL1 induced IGF2, H19, and CDKN1C expression in a prostate cancer cell line." (PMID 26115033, 2016). "Consequent expression analyses in the prostate cancer tissues showed a significantly diminished expression of the imprinted genes PLAGL1/ZAC1 (OMIM 603044), MEG3 (OMIM 605636), NDN (OMIM 602117), CDKN1C, IGF2, and H19, whereas KCNQ1OT1 was significantly overexpressed." (PMID 35804856, 2022). "Besides, GATA2 is a pioneer transcription factor for androgen receptor (AR) in prostate cancer, and increased GATA2 and its AR-independent transactivation of IGF2 could mediate taxane resistance through the activation of IGF1/insulin receptor signaling." (PMID 30935420, 2019). "Interestingly, also AR negative malignant prostate cancer cells (PC-3) exhibit an increased IGF-2 expression like LNCaP at higher AA concentration." (PMID 25332874, 2014). "Our results suggest that IGF-1, IGF-2, and IGFBP-3 measurements have no value in cancer screening, although IGF-1 and IGF-2 may be of aetiological significance in relation to colorectal and prostate cancer." (PMID 16804529, 2006).
ovarian carcinoma (70 papers, 2006 to 2025). A malignant neoplasm originating from the surface ovarian epithelium. "For example, elevated IGF1 and IGF2 expression were linked to disease progression and poor survival in ovarian cancer." (PMID 26861122, 2016). "In ovarian cancer patients, high IGF2 expression in tumor tissue is associated with clinically evident drug resistance, as we have now shown in two independent cohorts." (PMID 24932685, 2014). "High IGF2 expression is also strongly associated with ovarian cancer and stem cell-like neuroblastoma." (PMID 25423083, 2014). "We have shown that IGF2 overexpression in ovarian cancer is associated with hypermethylation of CTCF binding sites within the IGF2/H19 imprint center." (PMID 23745176, 2013). "In conclusion, elevated IGF2 expression in epithelial ovarian cancers is associated with increased methylation of a novel regulatory sequence motif that we have shown binds to the CTCF protein." (PMID 23745176, 2013). "IGF2BP1 regulates the growth factor IGF2, and knockouts of the gene in mice suggest a role in organ development, while its expression is associated with ovarian cancer." (PMID 20195514, 2010). "This increase in IGF2 expression in colon and ovarian cancer is likely the result of a loss of imprinting as both the maternal and paternal forms of this gene are seen in a significant number of these patients." (PMID 19732452, 2009). "In ovarian cancer, the expression of IGF2 is associated with HGSOC and advanced stages." (PMID 41007637, 2025). "In addition to its association with poor patient prognosis, IGF2 is involved in cancer drug resistance, particularly concerning the most commonly used chemotherapy agents in ovarian cancer." (PMID 41007637, 2025). "In patients with epithelial ovarian cancer, loss of heterozygosity of both Igf2 and H19 genes tend to be found in advanced clinical stages of ovarian cancer, loss of imprinting of Igf2 and H19 genes may be contributed to the development of ovarian cancer." (PMID 29921308, 2018). "Since Taxol is used in the first-line treatment of ovarian cancer, we hypothesized that high IGF2 would be associated with intrinsic clinical drug resistance, manifesting as decreased time to disease progression/recurrence in patients." (PMID 24932685, 2014). "Insulin-like growth factor-II (IGF2) encodes a potent autocrine and paracrine mitogen that is important to early growth and development, but is also often deregulated in cancers, including colon and ovarian cancers where it has been shown to modulate taxol response." (PMID 23745176, 2013). "PLAG1 silencing can inhibit the sensitivity of ovarian cancer cells to cisplatin through IGF2 signaling pathway." (PMID 40276502, 2025). "IGF2 can enhance the glycolytic pathway and promote the migration, invasion and proliferation of ovarian cancer cells." (PMID 40309242, 2025). "Long non-coding RNA (LncRNA) MCF2L-AS1 contributes to cisplatin resistance of ovarian cancer via regulating the IGF2BP1/IGF2/MEK pathway." (PMID 39759028, 2024). "Ovarian cancer patients with high ascites levels of IGF-1 or IGF-2 showed a poorer prognosis reflected in shorter overall survival." (PMID 38396692, 2024). "IGF2 mRNA binding protein 1 (IGF2BP1) belongs to the IGF binding protein family, and an ovarian cancer risk score model showed that IGF2BP1 shared great value in the prognostic analysis of ovarian cancer cases." (PMID 37304234, 2023). "It has been shown that hypermethylation of CTCF-binding site at the H19/ICR increased expression of IGF2 in ovarian cancer." (PMID 35459174, 2022). "In a number of ovarian cancer cell lines, IGF-2 expression has been higher in Taxol-resistant cells compared with chemosensitive cell lines." (PMID 33768092, 2021). "Our study found that TMED2 regulates epithelial ovarian cancer progression by activating IGF2/IGF1R/PI3K/AKT pathway." (PMID 29212217, 2017).